LCN2 (lipocalin 2)
Diseases named in the same sentence as LCN2 in open-access papers (continued):
Sharing a sentence is not in itself a finding about the gene and the disease.
diabetes (164 papers, 2010 to 2026). "Further research remains necessary to elucidate the biological relevance of LCN2-linked TREM2 in diabetes." (PMID 35884685, 2022). "On the other hand, it is also noticeable that LCN2 is a promising diagnostic biomarker and drug target in neuropathy of diabetes." (PMID 35966090, 2022). "In this regard, LCN2 can be considered one of the mediators responsible for inflammation in complications associated with diabetes." (PMID 33613327, 2021). "Recently, a study reported the upregulation and pathological role of LCN2 in the hippocampus of an insulin-deficient diabetes model created by streptozotocin injection." (PMID 33613327, 2021). "LCN2 is particularly associated with several brain injuries such as ischemic stroke, diabetes, dementia, and encephalomyelitis." (PMID 34844610, 2021). "Preliminary findings have shown that LCN2 is also a promising drug target and diagnostic marker for the treatment of neuropathic complications from diabetes." (PMID 33613327, 2021). "Increased level of circulating LCN2 has been considered an inflammatory marker closely associated with insulin resistance and hyperglycemia in patients with diabetes." (PMID 30761088, 2019). "Earlier studies found Lipocalin-2 elevated in complications associated with type 2 diabetes mellitus such as ischemic heart disease." (PMID 28709459, 2017). "The circulating GDF15 level was positively associated with age, smoking, hypertension, and diabetes mellitus as well as circulating levels of lipocalin 2 and various biomarkers of inflammation and oxidative stress." (PMID 28798540, 2017). "Additionally, clinical and experimental evidence has demonstrated the association between LCN2 levels and microvascular complications of diabetes, including diabetic neuropathy." (PMID 40951890, 2025). "Lipocalin-2 has been studied foremost in obese/overweight patients and type 2 diabetes showing association to retinopathy but significantly correlation with a decreased glomerular filtration rate has been shown in young adults with typ1 1 diabetes." (PMID 38932813, 2024). "This leads to the hypothesis that TREM2 may be a potential target for the treatment of diabetes-associated inflammation by establishing a connection between LCN2-mediated neuroinflammation and microglial activation." (PMID 35884685, 2022). "Additionally, logistic regression analysis demonstrated that LCN2 (odds ratio (OR) = 1.009) and diabetes duration (OR = 1.058) were independently associated with the occurrence of DPN in T2D." (PMID 34636748, 2021). "Moreover, diabetes-associated cognitive deficits were improved in Lcn2 knockout mice compared to WT mice in diabetic conditions." (PMID 34636748, 2021). "Based on these findings, it is suggested that LCN2-mediated neuroinflammation may be a potential mechanism underlying diabetic encephalopathy and cognitive deficit in both type 1 and type 2 diabetes mellitus." (PMID 30761088, 2019). "Moreover, Lcn2-deficient mice showed decreased neuronal loss in the CA1 region of the hippocampus following diabetes, an effect that was correlated with improved cognitive behavior in these animals." (PMID 30761088, 2019). "As an alternative method to confirm whether Lcn2 deficiency ameliorates diabetes-induced memory dysfunction, we used the Y-maze test, which measures the natural behavioral tendency of mice to explore new environments." (PMID 30761088, 2019). "Hence, increased lipocalin-2 production by bones could be a protective response to diabetes-associated bone loss." (PMID 36831188, 2023). "However, Lcn2 deficiency ameliorated this diabetes-induced memory dysfunction." (PMID 30761088, 2019). "Most previously published studies evaluating urinary lipocalin-2 excretion were conducted among patients with diabetes duration longer than six years." (PMID 40004620, 2025).
diabetes (continued). "There is evidence linking LCN2 to the exacerbation of ischemic stroke in an STZ-induced diabetes model system, with such toxicity being attributable to neutrophil-derived ferroptosis." (PMID 40270596, 2025). "Further, Lipocalin-2 (LCN-2) also serves as a crucial prognostic marker of renal injury in diabetes and hypertension." (PMID 38835661, 2024). "A previous study shows that LCN2 released from astrocytes activates microglia, further aggravating diabetes-induced neuroinflammation." (PMID 38201988, 2024). "Since diabetes is known to compromise several antimicrobial peptides like hBD-1, RNase4, RNase7, and LCN2, our results are of special relevance and suggest a mode to reestablish the expression of antimicrobial peptides in type 2 diabetes patients." (PMID 34651203, 2022). "Our previous study and other colleagues’ studies indicate that serum LCN2 levels are significantly higher in diabetes and diabetic complications such as diabetic retinopathy, diabetic nephropathy, and cardiovascular diseases." (PMID 34636748, 2021). "Under the conditions of diabetes, LCN2 from satellite glial cells mediates macrophage infiltration into DRG, stimulates the release of inflammatory cytokines such as tumor necrosis factor-α, and enhances neuronal inflammatory response." (PMID 34636748, 2021). "Recently, the number of studies describing a role for LCN2 in metabolic homeostasis and the pathogenesis of diabetes-related complications is on the rise, indicating similar importance of LCN2 in diabetes-related neurological disorders." (PMID 33613327, 2021). "A variety of studies have demonstrated the role of lipocalin 2 (LCN2) in both diabetes and neurological disorders." (PMID 34636748, 2021). "As TonEBP and LCN2 have several roles in common for chronic low-grade inflammation in diabetes, functional connections between them in macrophage-mediated neuroinflammation would be expected in the diabetic brain." (PMID 34844610, 2021). "In this study, deletion of the Lcn2 gene ameliorated diabetes-induced reactive gliosis and expression of proinflammatory cytokines in the hippocampus of diabetic mice." (PMID 33613327, 2021). "Deletion of Lcn2 gene ameliorated diabetes-induced reactive gliosis and expression of pro-inflammatory cytokines in the hippocampus, subsequently decreasing neuronal loss in the hippocampus." (PMID 34636748, 2021). "The independent factors for DPN were LCN2 (odds ratio (OR) = 1.009) and diabetes duration (OR = 1.058), respectively." (PMID 34636748, 2021). "For example, the expression levels of genes relevant to cholesterol and lipoprotein transport, such as Apoa1-2/Apoc1-3/Lcn2/Rbp4, showed reversed phase between the diabetes and diabetes-DFE groups." (PMID 31790971, 2020). "LCN-2 expression was induced by agents promoting insulin resistance and was suppressed by insulin-sensitizing anti-diabetes drug." (PMID 32982804, 2020). "To study the role of LCN2 in the pathogenesis of diabetic encephalopathy, we used multiple animal models of diabetes in this study, including the multiple low dose STZ injection (MLDS), high dose STZ injection (HDS), and high fat diet (HFD) feeding models." (PMID 30761088, 2019). "Here, we show that induction of diabetes increased the expression of both Lcn2 mRNA and protein in the hippocampus." (PMID 30761088, 2019). "In this study, we investigated the role of LCN2 in multiple aspects of diabetic encephalopathy in mouse models of diabetes." (PMID 30761088, 2019). "Further, deletion of the Lcn2 gene ameliorated the diabetes-induced reactive gliosis in the hippocampus seen in the WT-diabetic mice." (PMID 30761088, 2019). "Further, the circulating levels of LCN2 have been reported to be increased in both rodents and patients with diabetes." (PMID 30761088, 2019). "In this study, we used mouse models of diabetes to examine the pathological role of LCN2 in the progression of diabetic encephalopathy." (PMID 30761088, 2019).
diabetes (continued). "Several in vivo studies have revealed the effect of STZ-induced diabetes on LCN2 expression in the peripheral tissues of rodents." (PMID 30761088, 2019). "Further, diabetes-induced hippocampal toxicity and cognitive decline were both lower in Lcn2 knockout mice than in the wild-type animals." (PMID 30761088, 2019). "In the setting of dominating inflammatory medium of diabetes, the expression, and secretion of LCN2 increases stridently due to the conversion of preadipocytes to mature adipocytes." (PMID 30534206, 2018). "This study aimed to investigate the level of lipocalin-2, glycated hemoglobin (HbA1c) in Sudanese patients with type 2 diabetes mellitus." (PMID 28709459, 2017). "SHBG and PRSS2 might explain the beneficial association with IHD; testosterone, SHBG, CCL5, CNDP1, F11, LCN2, and THBS4 might explain the association with diabetes, which provides insights for drug development." (PMID 41882153, 2026). "This includes conditions such as asymmetric carotid stenosis and comorbidities like hypertension and diabetes, which could impact the temporal and spatial expression patterns of LCN2." (PMID 40365739, 2025). "In addition, studies revealed that TonEBP promotes neuroinflammation and cognitive impairment via the upregulation of LCN2 in mice in a diabetes model." (PMID 38188678, 2023). "In addition to restricting iron availability, LCN2 also exerts a cytoprotective effect against STZ in a short-term HFD mouse model of diabetes by improving β-cell mass and promoting β-cell proliferation." (PMID 36430158, 2022). "Indeed, an increased serum level of lipocalin-2 in patients with diabetes mellitus compared to healthy controls was described." (PMID 35639706, 2022). "The role of LCN2 in neurological complications of diabetes has also been studied." (PMID 36536319, 2022). "LCN2 expression is elevated by agents that promote IR and is reduced by PPARγ agonists thiazolidinediones (TZDs), an important class of insulin sensitizers used in the treatment of diabetes." (PMID 36079831, 2022). "Lcn2 was found to be a biomarker for the coexistence of liver injury not only induced by alcohol but when there is liver involvement in inflammatory arthritis or in type-2 diabetes mellitus patients with hepatitis B co-infection." (PMID 34327512, 2021). "The LCN2 levels are known to be elevated in circulation in diabetes." (PMID 34636748, 2021). "In chronic conditions such as diabetes, over-secretion of LCN2 in the hippocampus may subsequently aggravate the neural imbalance in the hippocampus, and lead to impaired cognitive function." (PMID 30761088, 2019). "LCN2 was significantly elevated in patients with diabetes compared with controls." (PMID 28709459, 2017). "Patients with type 2 diabetes mellitus have elevated level of serum lipocalin-2." (PMID 28709459, 2017). "Second, No causal relationship between lipocalin-2 levels and the risk of impaired glucose regulation or diabetes can be drawn, since the study was cross-sectional designed." (PMID 22292925, 2012). "LCN2, for example, promotes insulin resistance and increases blood brain barrier (BBB) permeability (BBB leakage in the hippocampus is thought to be a cause of cognitive impairment in diabetes and AD), while GAL3 promotes oxidative stress and impairs learning and memory in diabetes patients." (PMID 39798403, 2025). "In addition, lipocalin-2 levels measured in first morning urine were associated with cardiovascular complications, independent of established risk factors and diabetes duration." (PMID 37189804, 2023). "Interestingly, the relationship between LCN2 and the neuropathy of diabetes is well demonstrated." (PMID 35966090, 2022). "Regarding its role in the onset of diabetes, a novel hypothesis is emerging: LCN2 may be upregulated during the earliest stage of diabetes to promote β-cell function and insulin sensitivity but this protective mechanism is eventually overwhelmed when diabetes settles." (PMID 34638803, 2021).
diabetes (continued). "Taken together, these findings suggest that LCN2 can mediate neuroinflammation via activation of glial cells and increased expression of inflammatory cytokines which leads to hippocampal neuronal death and impairs cognitive function across domains in patients with diabetes." (PMID 30761088, 2019). "It is difficult to draw any conclusions from previous studies compared to our results since lipocalin-2 and MMP-9 levels only significantly changed when comparing patients with a diabetes duration < 5 years." (PMID 38932813, 2024). "The aim of this study is to explore the relationship between serum lipocalin-2 (LCN-2) levels and DN and carotid atherosclerotic plaque (CAP) in patients with type 2 diabetes mellitus (T2DM)." (PMID 35547005, 2022). "We found that the induction of diabetes through STZ administration and HFD feeding significantly increased the expression of LCN2 in the hippocampus at the level of mRNA and protein." (PMID 30761088, 2019). "In the current study, we used STZ-induced diabetes and HFD mice models to evaluate the expression level of LCN2 in the hippocampus." (PMID 30761088, 2019). "This study aimed to investigate the levels of Retinol Binding Protein 4 (RBP4), Lipocalin-2, and high-sensitivity C-reactive protein (hsCRP) in individuals with impaired fasting glucose (IFG), impaired glucose tolerance (IGT), and type 2 diabetes mellitus (T2DM)." (PMID 40951890, 2025). "INV-202 treatment partially reduced tubular hyperplasia and blocked the negative effects of diabetes on lipocalin-2 protein expression." (PMID 37675364, 2023). "Genes (Apo family, Lcn2, and Rbp4, etc.)involved in lipid transport showed opposite expression profiles between the diabetes-DFE-VS-diabetes and diabetes-VS-normal comparisons, suggesting their critical roles in decreasing lipid infiltration under DFE administration." (PMID 31790971, 2020). "Other studies have reported increases in urinary excretion of kidney injury markers, including lipocalin 2 (Lcn-2), OPN, α-glutathione S-transferase (α-Gst), μ-glutathione S-transferase (μ-Gst), and beta-2 microglobulin (β2m) in diabetes and ischemic or nephrotoxic injury in both animals and humans." (PMID 25243053, 2014). "When investigating FGF21, Cystatin C, lipocalin-2, and MMP-9 in this study from diagnosis of type 1 diabetes over time, Cystatin C showed most promising results with increased values from diagnosis to follow-up and inverse correlation to HbA1c and duration of diabetes." (PMID 38932813, 2024). "This is in contrast with a previously published article in which LCN2 levels were higher in patients with diabetes than in non-diabetic patients, as well as some studies that have reported a correlation between LCN2 and age, but which were conducted on patients without an acute infection." (PMID 37317134, 2023). "However, the expression of LCN2 in the brain has not yet been studied using a mouse model of STZ-induced diabetes." (PMID 30761088, 2019). "Circulating levels of lipocalin-2 and RBP4 are positively correlated with carotid IMT and subclinical atherosclerosis in type 2 diabetes, which suggests a potential role of these two lipid-binding chaperones in the pathogenesis of vascular complications of diabetes." (PMID 23799122, 2013). "In addition, diabetic lipocalin-2 KO mice show diminished STZ-induced Iba1 overexpression by microglia, limited macrophage infiltration and decreased pro-inflammatory cytokines expression including TNF-α and IL-6, supporting a role for lipocalin-2 in diabetes-induced brain inflammation." (PMID 36869375, 2023). "As compared to patients without END, patients with END were more likely to develop diabetes (p = .034) and had higher baseline NIHSS score (p = .009) and LCN2 levels (p = .021)." (PMID 36974345, 2023).
diabetes (continued). "Statistically significant differences in lipocalin-2 and MMP-9 could be observed when comparing patients with a diabetes duration < 5 years and patients with a diabetes duration of 5–10 years (P = 0.008 for both), but not in comparison to patients with a diabetes duration > 10 years." (PMID 38932813, 2024).
breast carcinoma (159 papers, 2008 to 2026). "It has been previously reported that high levels of LCN2 are found in IBC cells and patient tumors and that high LCN2 expression is associated with decreased prognosis and overall survival in patients with breast cancer." (PMID 40732340, 2025). "The tumor-promoting role of LCN2 has also been reported in cancers other than breast cancer, e.g., stromal cell-derived LCN2 is associated with poor differentiation and prognosis in oral squamous cell carcinoma." (PMID 40109857, 2025). "In particular, aggressive subtypes of breast cancer (BC) are associated with high LCN2 expression, highlighting it as a key regulator of metastasis formation." (PMID 41303420, 2025). "The previous study revealed that Lipocalin 2 (Lcn2) shows potential as a therapeutic target and diagnostic biomarker for breast cancer." (PMID 40125243, 2024). "In breast cancer, LCN2 has been linked to cellular differentiation through modulation of the epithelial to mesenchymal transition." (PMID 35013251, 2022). "Recently, however, therapeutic editing of a breast cancer oncogene (LCN2, encoding Lipocalin-2) has been achieved by using an innovative vehicle (tNLG: targeted-NanoLipoGel) for delivery of CRISPR-Cas9 plasmids in TNBC cells." (PMID 35326630, 2022). "LCN2 has been implicated in the evolution of breast cancer, through various mechanisms, such as EMT, angiogenesis, MMP-9 upregulation, apoptosis inhibition, and iron accumulation." (PMID 36077676, 2022). "On the contrary, LCN2 is positively associated with metastasis in breast cancer, anaplastic thyroid carcinoma cells and prostate cancer." (PMID 36428800, 2022). "Conversely, cervical, colorectal, ovarian, and breast cancer studies reported that the high level of lipocalin-2 expression was associated with poor differentiated tumors, higher lymph node metastasis, and higher tumor stage." (PMID 33542838, 2021). "In breast cancer, increased LCN2 expression was associated with poor outcomes and shown to be an independent prognostic marker of disease‐specific‐free survival." (PMID 34342930, 2021). "The role of LCN2 in cancer metastasis is further confirmed by the fact that its deficiency in murine breast cancer cells had resulted into a significant reduction in the size and metastasis of the primary tumors with a reduced MMP9 levels in blood." (PMID 34588926, 2021). "It has been reported that apoptotic tumor cells release S1P, and then stimulate the generation of lipocalin 2 (LCN2) in TAMs and is associated with breast cancer metastasis." (PMID 34283088, 2021). "Overexpression of LCN2 is also associated with the progression of aggressive forms of endometrial carcinoma, pancreas, and breast cancers." (PMID 34445288, 2021). "Our 3rd highly upregulated secretory mediator LCN2, is elevated in varieties of cancers, and is associated with breast cancer progression." (PMID 34072157, 2021). "Loss or reduced expression of nuclear LCN2 is related to the aggressive nature and poor outcome in breast cancer." (PMID 34072157, 2021). "Of our interest, we explore further to understand if a higher expression of LCN2 is linked to aggressiveness and advance stage of breast cancer using the METABRIC cohort." (PMID 34072157, 2021). "Enhanced levels of lipocalin-2 (Lcn-2) were previously also associated with reduced disease-free survival in breast cancer patients, while inhibition of Lcn-2 significantly reduced mammary tumor progression and metastasis." (PMID 34069743, 2021). "In this study, it has been reported that lipocalin-2 was a predictive marker for pathological complete response after neoadjuvant chemotherapy in the low-risk subgroup of breast cancer." (PMID 33542838, 2021). "Lipocalin 2 (Lcn2, also called as neutrophil gelatinase-associated lipocalin) is a member of the lipocalin family and a known target for breast cancer." (PMID 32884206, 2020).